CD44 (CD44 molecule (IN blood group))
Diseases named in the same sentence as CD44 in open-access papers (continued):
Sharing a sentence is not in itself a finding about the gene and the disease.
sarcoma (29 papers, 2005 to 2024). A usually aggressive malignant neoplasm of the soft tissue or bone. "CD44 rs187115 was associated with an increased risk of tumor-related death and lower drug sensitivity in sarcoma." (PMID 27323782, 2016). "In sarcomas, research on the roles of CD44 is conductive to understanding the pathogenesis of these rare cancers." (PMID 38783892, 2024). "Compelling evidence suggests that the overexpression of CD44 in most sarcomas participates in tumor progression, stemness, and dissemination." (PMID 38783892, 2024). "Further analysis of differentially methylated regions between tumors within the novel group and CIC-rearranged sarcoma showed aberrant methylation patterns, including promoter region hypomethylation amongst others of CD44, EMP3, and VIM in these tumors." (PMID 36964296, 2023). "CD44 is overexpressed in most sarcomas and several in vitro and in vivo experiments have shown a direct effect on tumor progression, dissemination, and drug resistance." (PMID 35785191, 2022). "Most of the studies carried out to understand the functionality of CD44 in cancer have been performed in epithelial tumors, although some relevant works focused specifically on sarcomas." (PMID 35785191, 2022). "In summary, there is a relatively high expression level of CD44 in MSCs and sarcomas according to different studies and publicly available datasets." (PMID 35785191, 2022). "HA oligomers therapies provide a viable alternative for blocking the CD44-HA interactions in sarcomas which has been only superficially explored, so that clinical trials should be performed to confirm this antitumoral approach." (PMID 35785191, 2022). "Summary of sarcoma subtype studies analyzing CD44 expression alone or in combination with other biomarkers in patient samples." (PMID 35785191, 2022). "In this review, we have gone through the information available on the role of CD44 in the development, maintenance, and progression of sarcomas, analyzing their implications at the prognostic, therapeutic, and mechanistic levels." (PMID 35785191, 2022). "In this review, we have gone through the information available on the role of CD44 in the development, maintenance, and progression of sarcomas and analyzed their implications at the prognostic, therapeutic, and mechanistic levels." (PMID 35785191, 2022). "Studies focused on MSCs, and sarcomas have shown CD44 to be highly expressed in these tissues compared to mature cells." (PMID 35785191, 2022). "Ewing sarcoma, an extremely rare sarcoma that arises mainly during childhood and adolescence, presents a notably reduced expression of CD44 compared to the rest of the sarcoma cell lines." (PMID 35785191, 2022). "The functional studies performed in different sarcomas demonstrate that CD44 plays a relevant role in sarcomagenesis and tumor progression." (PMID 35785191, 2022). "Synovial sarcomas exhibited lower CD68 and CD44 staining, and less macrophage infiltration than the other sarcomas in our study." (PMID 30999901, 2019). "Alterations in binding of hyaluronan to CD44 leads to the activation of invasion and metastasis in BC, sarcoma and GC." (PMID 27738347, 2016). "CD44 is a proapoptotic factor in FAS mediated apoptosis in sarcoma cells, but is also connected to cancer drug resistance.CD44 has successfully been used as a target for liposomal encapsuled doxorubicin." (PMID 18959781, 2008). "CD44 expression levels were high in most sarcoma cell lines except for the two Ewing sarcoma lines." (PMID 38177929, 2024). "CD44 is a well-established pro-metastatic gene in several malignancies, including some sarcomas." (PMID 37511533, 2023). "This phenomenon, regarding the downregulation of CD44 in comparison to other sarcomas, could be determinant for the tumor growth, dissemination, and drug resistance in this sarcoma subtype." (PMID 35785191, 2022). "However, as far as we know, no comprehensive review compiling the data concerning the role of CD44 in sarcomas has been published." (PMID 35785191, 2022).
sarcoma (continued). "Specifically, we identified two main populations of IFN–CSCs in MCA205 sarcoma cells: the CD133+CD24+CD44+low (CD44L, ~7 times higher compared with the untreated condition, (CTR)) and the CD133+CD24+CD44+high (CD44H, ~9 times higher compared with the CTR) CSC subsets." (PMID 36002648, 2022). "Therefore, the study of the similarities and differences among different grades of cell differentiation, that is, mesenchymal stem cells, sarcoma cells, and normal differentiated cells, is important to understand the role of CD44 in sarcomas." (PMID 35785191, 2022). "Concordantly, CD44 is expressed at high levels in most sarcomas." (PMID 35785191, 2022). "Further research involving the sarcoma functional mechanisms could be really enriching in the characterization context of sarcoma, as well as, in the therapeutic approaches targeting CD44." (PMID 35785191, 2022). "To conclude, more research about the contribution of CD44 in sarcomas could contribute to understand the pathogenesis of these rare cancers, and evolve towards novel therapies and future clinical trials." (PMID 35785191, 2022). "Since CD44 is expressed at high levels in most types of sarcoma, inhibition of CD44 expression could have therapeutic usefulness." (PMID 35785191, 2022). "Several studies have analyzed the prognostic value of CD44 expression in sarcomas." (PMID 35785191, 2022). "The role of CD44 as a CSC marker in sarcomas has also been suggested by others." (PMID 35186752, 2022). "CD44 expression has been demonstrated in a number of sarcoma cell lines and patient material." (PMID 22911243, 2012). "Moreover, we illustrate how research involving the specific role of CD44 in the different sarcoma subgroups could suppose a chance to advance towards a more innovative perspective for novel therapies and future clinical trials." (PMID 35785191, 2022). "Therefore, there is an untested group of anti-CD44 blocking antibodies, which may have therapeutic potential in the context of sarcomas, but further research is needed." (PMID 35785191, 2022). "Next, we analyzed if the low expression of CD44 in A673 cells (EWSR1::FLI1high) was also observed in other Ewing sarcoma cells and/or other sarcoma types." (PMID 37511533, 2023). "We exposed human sarcoma cell lines to sorafenib, regorafenib, and pazopanib and assessed cell viability and expression of CSC markers (ALDH, CD24, CD44, and CD133)." (PMID 25301268, 2014). "Analysis of genes that characterize MSCs such as CD44, CD105, CD73, and CD90 showed higher expression in MSCs compared to sarcomas." (PMID 22852096, 2012). "Mesenchymal stem cell markers, CD44, CD73, CD90, and CD105 were all strongly expressed in MSCs compared to both sarcomas." (PMID 22852096, 2012). "High expression of CD44, EMP3 and VIM may be useful to distinguish the tumors from CIC-rearranged sarcoma." (PMID 36964296, 2023). "The role of CD44 in tumor progression, invasion, and metastasis has been well established in many cancers, although a comprehensive review concerning its role in sarcomas has not been published." (PMID 35785191, 2022). "In this study, the differences observed between the serum levels of CD44 in children with sarcoma and healthy controls were not significant (p>0.05), as result, a non-diagnostic or prognosis value was established." (PMID 35785191, 2022). "Although several studies have shown a relevant role of CD44 in a reduced number of sarcomas, there is a clear lack of studies in other types of sarcomas such as myxofibrosarcoma, synovial sarcoma, or rhabdomyosarcoma, among others." (PMID 35785191, 2022). "In addition, we found a significant increase in the population of cells with CSC-like properties owing to the increment in CD44+/CD24− percentage in T-47D cell line and also in CD133+ population in sarcoma cell lines." (PMID 33106480, 2020).
sarcoma (continued). "After administration of the PCI-photosensitizer TPCS2a and ITx in seven different carcinoma and sarcoma cell lines an efficient and specific cytotoxicity in CD44-expressing but not in CD44-negative cancer cells was observed." (PMID 29438358, 2018). "In addition, this study also described that the undifferentiated intimal sarcoma cells were positive for mesenchymal stem cell markers, such as RUNX-1 or CD44." (PMID 24489925, 2014). "Although CD44 has not been used as sarcoma CSC marker, it is a well-established CSC marker in other cancers." (PMID 22911243, 2012). "In contrast, we observed CD24, CD44, and CD133 to be variably expressed in our sarcoma cell lines, and we found that these markers did not reliably correlate with the CSC phenotype." (PMID 25301268, 2014). "PTPN2‐deficient CD8+ HER‐2 CAR T cells were more activated, as assessed by the expression of CD44, CD25, PD‐1 and LAG‐3, after overnight incubation with HER‐2‐expressing 24JK (24JK‐HER‐2) sarcoma cells, but importantly, not HER‐2‐negative 24JK control cells (Fig EV1B)." (PMID 31803974, 2020).
asthma (28 papers, 2011 to 2025). "Th2-mediated airway inflammation was caused by CD44–HA interactions through Neu1-meidated desialylation in the airway of asthma mouse model." (PMID 38500102, 2024). "Additional studies are needed to clarify the detailed role of CD44 in the development of chronic airway inflammation, such as human asthma, and to clarify the possible involvement of CD44 in other immune cell mechanisms underlying asthma pathophysiology." (PMID 35069598, 2021). "Overexpressed CD44 could further induce the expression of asthma-associated molecules, including IL-6, IL-8 and intercellular adhesion molecule 1 (ICAM), which promote progression of asthma." (PMID 29471827, 2018). "In addition, miR-708 also caused downregulation of expression of several ‘asthma-related’ genes such as CD44, ADAM33 and RARRES2." (PMID 26998837, 2016). "In asthma, CD44 overexpression facilitates eosinophil and neutrophil adhesion, driving airway infiltration and Th2-polarized inflammation." (PMID 40986971, 2025). "On the other hand, PLZF is essential for CD4+ T-cell development and can regulate the memory phenotype of CD44+ CD4+ T cells to promote the development of asthma tolerance." (PMID 39632661, 2024). "The results showed that the proportion of CD4+CD44+ T cells, especially CD4+ TRMs, is positively correlated with the severity of asthma symptoms caused by RSV infection, as well as several other molecular markers." (PMID 39632661, 2024). "Taken together, these findings suggest that the number of CD4+CD44+ memory T cells in lung tissue is highly positively correlated with the severe allergic symptoms of asthma induced by RSV infection, indicating a pulmonary-specific immune response." (PMID 39632661, 2024). "CD4+CD44+ T cells are closely related to the severity of asthma aggravated by RSV infection, and among the memory T cells, the enrichment of CD4+ TRMs in the lungs is the dominant change, which promotes the recurrence of early asthmatic pulmonary inflammation." (PMID 39632661, 2024). "The harmful effects of low-molecular-weight HA in asthma are mediated by binding CD44 and receptor for HA-mediated motility (RHAMM) receptors, CD44 and CD168, which precedes the release of pro-inflammatory cytokines." (PMID 35742845, 2022). "CD44-HA interactions critically contribute to the airway accumulation of allergen-specific Th2 cells in allergen-induced acute asthma mouse models." (PMID 35069598, 2021). "In previous studies, IL-13 has been reported to increase CD44 and CD44 isoform expression in a murine model of asthma and in colon epithelial cells, respectively." (PMID 27533463, 2016). "Osteopontin (OPN), another major ligand of CD44, is also involved in the immune and inflammatory responses in asthma and cigarette smoking." (PMID 26999446, 2016). "Of particular relevance to allergies and asthma, it has been shown that CD44 expression on DCs plays a crucial role in DC activation of T cells." (PMID 24381635, 2013). "Similarly, Gal-9 administration in a guinea pigs asthma model had a suppressing effect on eosinophils accumulation in lungs, due to the suppression of their CD44-dependent migration." (PMID 38785528, 2024). "It is also known that CD44-HA signaling has important regulatory roles largely based on its MW in various pulmonary diseases such as bacterial pneumonia, LPS-induced lung injury, ventilator-induced lung injury, and asthma." (PMID 34016170, 2021). "However, Klagas and colleagues have demonstrated reduced CD44 expression on airway smooth muscle cells during asthma and COPD." (PMID 26999446, 2016). "Cleaved sOPN has been suggested to interact with CD44 and may play a role in the pathogenesis of asthma through this mechanism." (PMID 22031818, 2011). "Previous studies evidenced that IL-5 upregulates the levels of CD11b and CD44 on human eosinophils which, together with the increased serum IL-5 levels found in severe vs. mild asthma, could explain the upregulation of these markers in our cohort of SEA patients." (PMID 41394834, 2025).
asthma (continued). "Several reports have suggested that CD4+CD44+ memory T cells are involved in RSV infection and asthma." (PMID 39632661, 2024). "Modified HMW-HA also interacts with CD44 to inhibit NF-κB activation, dendritic cell maturation, and allergen-specific CD4 T-helper reaction, potentially providing therapeutic effects to asthma and allergic sinusitis." (PMID 31067702, 2019). "These include CD44, a hyaluronan receptor, and CD48, whose levels are lower in poorly controlled or severe asthma compared to well-controlled or moderate disease." (PMID 28660189, 2017). "A possible explanation for this phenomenon is a high degree of ongoing extravasation of the most activated eosinophils, i.e., those with the highest level of CD44, CD48, and β1 integrin activation, in severe asthma." (PMID 28660189, 2017). "Altered expression of CD44 as well elements of TGF-β and EGFR signaling play a role in airway remodeling in asthma." (PMID 21572528, 2011). "Despite no changes were previously found in asthma compared to healthy, our results demonstrated a significantly higher surface expression of CD11b and CD44 on eosinophils from SEA patients." (PMID 41394834, 2025). "The cell surface adhesion receptor cluster of differentiation 44 (CD44) as a highly glycosylated molecule, interacted with hyaluronic acid (HA), to participate in the airway accumulation of CD4+ T cells in murine model of asthma." (PMID 38500102, 2024). "In fact, Gal-9 can bind CD44, a glycosylated adhesion molecule highly expressed on many human cells and involved in lymphocytes migration and airway hyperresponsiveness (AHR) development in asthma." (PMID 38785528, 2024). "In addition, expression of RARRES2, CD44 and ADAM33, genes known to contribute to the pathophysiology of asthma, were found to be inhibited in miR-708-transfected cells." (PMID 26998837, 2016).
nasopharyngeal carcinoma (28 papers, 2012 to 2023). A carcinoma arising from the nasopharyngeal epithelium. "Up regulation of CD44 in association with elevated levels of ROS was also reported in aggressive phenotype of nasopharyngeal carcinoma." (PMID 24489904, 2014). "Figshare: dataset for The Correlation between CD44+ cancer stem cell expression and histopathological type of nasopharyngeal carcinoma." (PMID 34804499, 2021). "Exosomal LMP1 activates the PI3K/AKT pathway, and then up-regulates the expression of the surface marker CD44+/High, ultimately increasing the populations of CD44+/High cells, which are the putative stem cell in nasopharyngeal carcinoma cells." (PMID 31122265, 2019). "For example, increased CEP55 expression was reported to promote EMT in nasopharyngeal carcinoma via the osteopontin/CD44 pathway." (PMID 26615423, 2016). "CD44 is one the proteins downregulated by miR-328 in human cells, and its expression is reported to be associated with EMT in nasopharyngeal carcinoma." (PMID 24919189, 2014). "CD44-Serglycin interaction maintains tumoral cell stemness through CD44 upregulation (as part of a positive feedback loop) mediated by MAPK/β-catenin pathway activation in nasopharyngeal carcinoma cells." (PMID 35785191, 2022). "CD44 has been reported to be a novel downstream target of microRNA-150 in nasopharyngeal carcinoma." (PMID 33303029, 2020). "Stable knockdown of Wnt5a in S18 nasopharyngeal carcinoma cells significantly decreased the percentage of CD24−/CD44+ stem-like cells, while over-expression of Wnt5a in S26 nasopharyngeal carcinoma cells S26 significantly increased the percentage of CD24−/CD44+ cells." (PMID 27571105, 2016). "In nasopharyngeal carcinoma, CD44 plays a role in the EMT phenotype of cancer stem-like cells." (PMID 24919189, 2014). "Chan's team discovered that EVs derived from nasopharyngeal carcinoma (NPC) cells exhibited high levels of ICAM-1 and CD44 variant 5 (CD44v5) expression." (PMID 37735659, 2023). "We found that nasopharyngeal carcinoma (NPC) cells with high expression of CD44 and CD24 proteins presented with pronounced CSC properties." (PMID 27521216, 2016). "Researchers have attempted to isolate nasopharyngeal carcinoma (NPC) CSCs through side population, and specific biomarkers, such as CD44, and CD24." (PMID 27521216, 2016). "The serglycin/CD44 signaling axis induces the expression of Nanog and activates NF-κB/claudin-1 axis in NSCLC and triggers MAPK/β-catenin signaling in nasopharyngeal cancer cells to foster EMT, cancer cell stemness, and drug resistance." (PMID 35494005, 2022). "Analogically, in nasopharyngeal carcinoma, tumor cell xenografts of the HK1 cell line with high expressions of CD44 and EpCAM showed a more rapid growth than the ones where tumor cells’ expression of CD44 was diminished." (PMID 33540535, 2021). "Conversely, overexpression of PGC1α induced MMP2 and CD44 expressions in non-metastatic nasopharyngeal carcinoma 6-10B cells." (PMID 27626695, 2016). "A recent study has shown that spheres derived from nasopharyngeal carcinoma (NPC) cells possess CSC properties, express stemness proteins (Oct-4 and Nanog) and drug-resistant genes (MDR-1 and ABCG2), and undergo the EMT through increased CD44 expression." (PMID 26064420, 2015).